MIR548AZ (microRNA 548az)
Synonyms: hsa-mir-548az
Gene: MicroRNA gene on chromosome 8 (119,325,171 to 119,325,265, forward strand). Ensembl gene ENSG00000276479.
Gene Ontology:
Biological process: miRNA-mediated post-transcriptional gene silencing
Cellular component: RISC complex
Homologues: Orthologues: chimpanzee MIR548AZ (100% identical). Paralogues in human: MIR548AA1 (80% identical), MIR548K (79% identical), MIR548Z (78% identical), MIR548AY (77% identical), MIR548H3 (77% identical), MIR548X2 (75% identical), MIR548AN (74% identical), MIR548F3 (74% identical), MIR548F1 (72% identical), MIR548P (71% identical), MIR548N (68% identical), MIR548X (66% identical), and 13 more.